KIF2C (kinesin family member 2C)
Diseases named in the same sentence as KIF2C in open-access papers (continued):
Sharing a sentence is not in itself a finding about the gene and the disease.
breast cancer (continued). "KIF2C (Kinesin Family Member 2 C) is an important regulator of the cell cycle; and is highly expressed in a variety of tumors, such as Endometrial cancer, gliomas, breast cancer, and lung cancer; and has been shown to participate in tumor progression and metastasis." (PMID 38824541, 2024). "However, the role of KIF2C in immune cell infiltration of tumor microenvironment and immunotherapy in breast cancer remains unclear." (PMID 37016301, 2023). "Importantly, our results demonstrated that KIF2C may serve as an independent prognostic factor for breast cancer, which is different from age, tumor size, tumor stage, and other traditional biomarkers." (PMID 37016301, 2023). "KIF2C may be used as a new biomarker for predicting DOX resistance in breast cancer cases." (PMID 34663310, 2021). "Five hub genes (TPX2, KIF2C, CDCA8, BUB1B, and CCNA2) associated with the risk of distant metastasis were extracted for further research, which might be used as biomarkers to predict distant metastasis of breast cancer." (PMID 31285741, 2019). "The expression of KIF2C was analyzed using Tumor Immune Estimation Resource (TIMER) database and further verified by immunohistochemical staining in human breast cancer tissues." (PMID 37016301, 2023). "However, whether KIF2C has any effect on immunity response in breast cancer remains unknown." (PMID 37016301, 2023). "Further, KIF2C bound to PKM2 and modulated PKM2 stability to regulate autophagy and glycolysis in DOX-resistant breast cancer cells." (PMID 34663310, 2021). "The data suggest that KIF2C and ESR1, two co-expressed hub genes, are also positively and negatively correlated with the aggressive and metastatic nature of breast cancer, respectively." (PMID 34172056, 2021). "We found that KIF2C was highly expressed in DOX-resistant breast cancer tissues and cells, and that KIF2C overexpression decreased DOX sensitivity, in part through autophagy in breast cancer cells." (PMID 34663310, 2021). "Knocking down of KIF2C, KIF3C, KIF22, KIF18A and KIF24 inhibited proliferation of breast cancer cells via different mechanisms including G2/M phase arrest, delayed exit from mitosis, deregulating cell division and restoring ciliation." (PMID 32322170, 2020). "Cluster 2 (KIF2C, NDC80, NUF2) is also in agreement with the molecular subtypes and has the expression pattern similar to Cluster 1 in breast cancer patients." (PMID 31260503, 2019). "As already shown in breast cancer, we also find several members of the Kinesin protein family (KIF11, KIF15, KIF23, KIF2C and KIFC1) to be upregulated in patients with high expression of ATAD2." (PMID 26308378, 2015). "Of these, six genes (ABAT, DEPDC1, KIF2C, SMAD4A, TAF1D, and TUBB6) have been reported to be directly relevant to cancer mechanisms, such as mammary tumor progression (P = 0.046)." (PMID 23185353, 2012). "Specifically, over-expression of ANLN and KIF2C, and under-expression of MAPT strongly correlated with poor outcomes in breast cancer patients." (PMID 21679412, 2011). "The over-expression of ANLN and KIF2C, and the under-expression of MAPT consistently showed a strong correlation with poor survival in the breast cancer patients from both validation datasets." (PMID 21679412, 2011). "In breast cancer, there is also evidence that the CDK1/CCNB1/PLK1 axis may be one of the potential pathways by which KIF2C affects tumor progression." (PMID 41333555, 2025). "Consistent with the results from the TIMER database, a significantly higher level of KIF2C expression was observed in breast cancer tissues than in normal tissues in both the TCGA database and the GSE36295 dataset." (PMID 37016301, 2023).
breast cancer (continued). "A number of studies have demonstrated abnormal expression of KIF2C in cancers such as breast cancer, oral tongue cancer, hepatocellular carcinoma, and non-small cell lung cancer.22,26,50,51." (PMID 37717078, 2023). "KIF2C has been reported to be involved in the proliferation and migration of hepatocellular carcinoma and breast cancer; however, no studies have shown that KIF2C is related to the occurrence and development of pancreatic cancer." (PMID 36900292, 2023). "In addition, KIF2C was targeted by TBX15/miR-152, which inhibited autophagy and glycolysis in DOX-resistant breast cancer cells." (PMID 37328486, 2023). "Analysis of gene expression data of various gene expression synthesis (GEO) datasets for breast cancer using genetic algorithms and bioinformatics tools showed that FAM134B combined with KIF2C, ALCAM, and KIF2A may identify certain subtypes of breast cancer." (PMID 33199694, 2020). "Although 1222 target genes of miR-10b-5p were predicted and 48 significantly negatively correlated genes were obtained, only 5 overlapped genes, BIRC5, E2F2, KIF2C, FOXM1, and MCM5, were considered as potential key targets of miR-10b-5p in breast cancer for further analysis." (PMID 31579605, 2019). "Finally, five hub genes (TPX2, KIF2C, CDCA8, BUB1B, and CCNA2) were identified for further research, which might be used as promising biomarkers to evaluate the distant metastasis of breast cancer." (PMID 31285741, 2019). "However, the effect of KIF2C on OS in breast cancer patients was not significant." (PMID 41333555, 2025). "Thus, the oncogenic role played by KIF2C in breast cancer may not be the dominant mechanism of tumor progression." (PMID 41333555, 2025). "Additionally, we found that Domain-2 of KIF2C was crucial for the interaction between KIF2C and PKM2; and that Domain-2 of KIF2C promotes PKM2 stability which may regulate miR-152-induced DOX sensitivity in breast cancer cells." (PMID 34663310, 2021). "In addition, we confirmed that the expression levels of the three genes, ASPM, CDCA8 and KIF2C, were significantly reduced following the knockdown or silencing of FOXM1 based on both microarray data in BT-20 breast cancer cells (GSE2222) and RNA-seq data in MCF-7 breast cancer cells (GSE58626)." (PMID 33667222, 2021).
hepatocellular carcinoma (25 papers, 2020 to 2026). A malignant tumor that arises from hepatocytes. "In hepatocellular carcinoma, KIF2C overexpression has been linked to increased tumor cell invasion and metastasis through modulation of cytoskeletal dynamics and focal adhesion functions." (PMID 40292920, 2025). "Consistently, KIF2C has been shown to be positively associated with immune cell infiltration in glioma and hepatocellular carcinoma." (PMID 37016301, 2023). "Besides, KIF2C/4A/10/11/14/18B/20A/23 were also reported to be associated with the poor prognosis and promoted cell proliferation in hepatocellular carcinoma." (PMID 38713252, 2024). "Startlingly, nuclear ANLN has been shown to form a transcriptional complex with SP1, thus enhancing KIF2C transcriptional activity and activating the mTORC1 pathway, which leads to the hepatocellular carcinoma bone metastasis." (PMID 41513610, 2026). "KIF2C, which is highly expressed in hepatocellular carcinoma, has been identified as a direct target of the Wnt/β-catenin pathway." (PMID 38250721, 2024). "In summary, we found that HSG (PTTG1, ANLN, KIF2C, TPX2) was significantly upregulated in hepatocellular carcinoma and that the constructed prognostic risk model can reliably predict the prognosis of hepatocellular carcinoma patients." (PMID 38887516, 2024). "Among them, TYMS, KIF2C, UBE2C, and HJURP are associated with unfavorable prognosis in hepatocellular carcinoma, possibly due to the malignant growth of cells." (PMID 37035748, 2023). "For example, KIF2C has been revealed as a target of the mTORC1 and Wnt/β-catenin signaling in hepatocellular carcinoma." (PMID 34650608, 2021). "KIF2C has also been reported as a putative oncogene that is highly expressed in hepatocellular carcinoma non-small-cell lung cancer, colorectal cancer, glioma, and gastric cancer." (PMID 34650608, 2021). "Finally, a study in hepatocellular carcinoma has suggested that TBC1D7 interacts with kinesin family member 2C (KIF2C), which is highly expressed in some human tumours and a direct target of the Wnt/β-catenin pathway." (PMID 40655946, 2025). "Wnt/ βcatenin increases KIF2C gene expression in hepatocellular cancer." (PMID 39911278, 2025). "Furthermore, high expression of KIF2C was correlated to disease-free survival of hepatocellular carcinoma." (PMID 38344808, 2024). "In hepatocellular carcinoma, KIF2C expression is up-regulated by Wnt/β-catenin signaling." (PMID 37016301, 2023). "Furthermore, KIF2C has been reported to be correlated with immune cell infiltration in glioma, hepatocellular carcinoma and endometrial cancer." (PMID 37016301, 2023). "Recently, studies have revealed that KIF2C is overexpressed in hepatocellular carcinoma tissues." (PMID 34650608, 2021). "In hepatocellular carcinoma (HCC), KIF2C can promote epithelial-mesenchymal transition (EMT) for HCC progression." (PMID 35685442, 2022).
glioma (20 papers, 2016 to 2025). A benign or malignant brain and spinal cord tumor that arises from glial cells (astrocytes, oligodendrocytes, ependymal cells). "The first report of KIF2C’s association with the malignancy of gliomas was published by Bie and colleagues in 2012." (PMID 38344808, 2024). "Further analysis revealed an evidently positive association existing in KIF2C expression and the advanced stages of gliomas." (PMID 35387222, 2022). "We found an evidently positive association existing in KIF2C expression and the advanced stages of gliomas." (PMID 35387222, 2022). "In addition, multi-Cox regression analysis data indicated that only KIF2C expression and age displayed an association with glioma patient prognosis." (PMID 35387222, 2022). "Similarly, previous retrospective studies also detected an association between elevated levels of KIF-2C expression and lower histopathological grade of gliomas as well as higher tumor invasion in patients with gastric cancer and colorectal cancer." (PMID 27563815, 2016). "This unfavorable relationship between the expression of KIF2C and the OS of glioma patients was further reinforced by three reports showing that KIF2C was an important hub gene in the overall TCGA glioma dataset, low-grade gliomas and secondary glioblastomas." (PMID 38344808, 2024). "Their work indicated that KIF2C gene and protein expression was related to glioma grading and patient OS." (PMID 38344808, 2024). "In grade III glioma patients, we observed that higher expression of KIF2C presented a correlation with shorter survival time in both primary and recurrent gliomas." (PMID 35387222, 2022). "Further analysis also confirmed that KIF2C expression had an obvious positive correlation with the advanced grades of gliomas." (PMID 35387222, 2022). "We in-depth established a monograph containing the prognostic factors, such as KIF2C expression, age, and radiation therapy, to supply a quantitative base to forecast the possibility of one-year, three-year, and five-year OS in glioma patients for clinicians." (PMID 35387222, 2022). "Survival curve of the gene was also generated to evaluate the correlation between KIF2C expression and survival time in primary and recurrent gliomas using CGGA data." (PMID 35387222, 2022). "The result showed that KIF2C expression, age, grade, and radiation therapy were evident factors that were related to glioma prognosis." (PMID 35387222, 2022). "In order to validate the assumption that KIF2C was an independent factor for prognosis of gliomas patients, we conducted univariate and multivariate Cox regression analysis." (PMID 35387222, 2022). "In this study, we found KIF2C expression level presented a great positive correlation with the advanced stages of gliomas." (PMID 35387222, 2022). "Other co-expressed genes are also involved in the progression of glioma, such as KIF2C, DLGAP5 and CCNB1." (PMID 36040678, 2022). "Our results showed that higher expression of KIF2C correlated with shorter survival time in both primary and recurrent gliomas." (PMID 35387222, 2022). "In the present study, we analyzed the correlation between KIF2C expression and immune infiltration in gliomas using the Xcell dataset." (PMID 35387222, 2022). "Previous studies have demonstrated that high KIF2C expression can serve as an independent marker of poor prognosis in several tumors, including glioma, colorectal cancer, and gastric cancer 26-28." (PMID 33403046, 2021). "Aberrant kinesin family member 2C (KIF2C) expression in glioma has been confirmed and predicted as a potential independent prognosis marker for glioma patients." (PMID 32642801, 2020). "The identified DryNB included seven genes (KIF2C, CCNA2, NDC80, KIF11, KIF23, ANLN and CENPM) that were significantly associated with drug sensitivity or resistance of glioma patients to the targeted therapies." (PMID 31682596, 2019).
glioma (continued). "The clinical data verified the association of the identified genes (i.e., KIF2C, CCNA2, NDC80, KIF11, KIF23, ANLN, and CENPM) with the targeted therapy response and prognosis of glioma patients." (PMID 31682596, 2019). "In patients with gastric cancer, colorectal cancer, and glioma, elevated KIF-2C expression serves as an independent marker of poor prognosis." (PMID 27563815, 2016). "The data showed different degrees of KIF2C expression in multiple histology of gliomas." (PMID 35387222, 2022). "A previous study showed KIF2C is a marker for prognosis in human gliomas." (PMID 35387222, 2022). "Previous studies reported that the high expression of KIF2C could serve as an independent marker of poor prognosis in several tumors, including glioma, colorectal cancer, and gastric cancer, but the roles in BC reported less." (PMID 34384030, 2021). "Many studies have indicated that KIF2C expression likely functions in cancer progression and development, including esophageal squamous cell carcinoma, non-small cell lung cancer, and gliomas." (PMID 32305958, 2020). "In addition, the expression level of KIF2C mRNA has been identified as a potential independent biomarker for assessing glioma patient prognosis." (PMID 31285741, 2019). "Finally, KIF2C was higher in recurrent samples than primary glioma samples." (PMID 35387222, 2022). "Moreover, our results showed that higher expression of KIF2C correlated with shorter survival time in both primary and recurrent gliomas and could act as a potential biomarker for the prognosis of GBM." (PMID 35387222, 2022). "This analysis confirmed significantly upregulation of LRGs score and its core genes (KIF2C, CALD1, HSPE1, and IFI16) in glioma versus normal tissues." (PMID 41035644, 2025). "After calculating the hazard ratio and confidence interval, we observed that 8 hub genes in hub network 1 were related to the poor prognosis of gliomas, including PBK, KIF2C, CENPE, KIF14, MND1, FAM83D, NEIL3, and CDKN3." (PMID 35387222, 2022). "In grade II glioma patients, we observed that higher expression of KIF2C was correlated with shorter survival time in primary, but not with recurrent gliomas." (PMID 35387222, 2022). "We then tested whether the temporal patterns of the prioritized 5 genes (i.e., KIF2C, CCNA2, NDC80, KIF11 and KIF23) could be used to predict drug sensitivities of different glioma cell lines." (PMID 31682596, 2019). "In addition, our results showed that KIF2C was higher in IDH1 wild-type samples than IDH1 mutant glioma samples, in 1p/19q noncodel samples than 1p/19q code glioma samples, and in recurrent samples than primary glioma samples." (PMID 35387222, 2022). "In addition, our results showed that KIF2C was higher in IDH1 wild-type samples than IDH1 mutant glioma samples, and KIF2C was higher in 1p/19q noncodel samples than 1p/19q code glioma samples." (PMID 35387222, 2022).
colorectal cancer (18 papers, 2008 to 2024). A primary or metastatic malignant neoplasm that affects the colon or rectum. "Their analysis found that the mutation of E403K in KIF2C, which interferes with protein conformation and stability, was associated with the development of colorectal cancer." (PMID 38344808, 2024). "This is in line with the high incidence of missense mutations or amplifications in the KIF2C gene in pancreatic adenocarcinoma or the mutation of E403K in KIF2C found in colorectal cancer patients." (PMID 38344808, 2024). "While the first identified upregulated KIF2C as one of four key proto-oncogenes in a comprehensive transcriptomic study of colorectal cancer tissue stages I-IV, adenocarcinoma and mucinous adenocarcinoma." (PMID 38344808, 2024). "Similar to gastric cancer, KIF2C was found to be overexpressed in colorectal cancer tissues from 195 patients when compared to the corresponding normal tissue." (PMID 38344808, 2024). "Conversely, KIF2C high expression is associated with good DFS (HR = 0.53, COX p = 0.013566) in colorectal cancer." (PMID 35153749, 2021). "Next, we detected the expression and distribution of PARPBP, KNSTRN, and KIF2C in colorectal cancer and performed a multiplex immunofluorescence staining in TMAs." (PMID 34568334, 2021). "Screening antibodies in colorectal cancer have identified NY-CO-58/KIF2C as a tumor antigen." (PMID 35720323, 2022). "NY-CO-58/KIF2C has been revealed as a tumor antigen by screening antibodies in colorectal cancer." (PMID 34650608, 2021). "KIF2C was shown to act as a tumor antigen that can elicit spontaneous and frequent CD41 T-cell responses of the Th1 type in colorectal cancer, in a process that is influenced by peripheral T-regulatory cells." (PMID 34568334, 2021). "Indeed, KIF-2C was capable of inducing spontaneous T cell responses in vivo resulting in frequently occurring and highly functional KIF2C-specific T cells in patients with colorectal cancer." (PMID 27563815, 2016).